CALHM2 (calcium homeostasis modulator family member 2)
Description:
Pore-forming subunit of Ca(2+) homeostasis modulator channels. Mediates ATP release from astrocytes and ATP-induced Ca(2+) influx in microglia thus regulating neuronal ATP and Ca(2+) homeostasis, synaptic transmission and neuroinflammatory response. May form intercellular gap junctions. The gating mechanism remains unknown.
Synonyms: FAM26B
Tractability: Small molecule: a structure with a bound ligand is known. Antibody: UniProt places it where antibodies can reach, with medium confidence; UniProt predicts a signal peptide or a membrane-spanning region; its Gene Ontology location is reachable by antibodies, with medium confidence. PROTAC: its protein half-life has been measured.
Gene: Protein-coding gene on chromosome 10 (103,446,784 to 103,452,780, reverse strand). Ensembl gene ENSG00000138172.
Subcellular location: Cell membrane
Subcellular location (Human Protein Atlas): Mitochondria; Nucleoplasm; Cytosol
Gene Ontology:
Molecular function: identical protein binding; monoatomic cation channel activity
Biological process: ATP export; positive regulation of apoptotic process; calcium ion import; regulation of microglial cell activation; regulation of synaptic plasticity; monoatomic cation transmembrane transport
Cellular component: plasma membrane
Genetic constraint (gnomAD): Loss-of-function variants: 18 observed, 22.02 expected, observed/expected ratio (o/e) 0.82, 90% interval 0.56 to 1.21. The upper end of that interval is the gene's LOEUF score, 1.21, which puts it in group 5 of 6, group 1 being the genes least tolerant of losing a copy. Missense variants: 411 observed, 455.66 expected, observed/expected ratio (o/e) 0.9, 90% interval 0.83 to 0.98. Synonymous variants: 193 observed, 201.25 expected, observed/expected ratio (o/e) 0.96, 90% interval 0.85 to 1.08.
Homologues: Orthologues: chimpanzee CALHM2 (99% identical), macaque CALHM2 (99% identical), pig CALHM2 (93% identical), mouse Calhm2 (92% identical), rat Calhm2 (92% identical), guinea pig CALHM2 (92% identical), rabbit CALHM2 (90% identical), tropical clawed frog calhm2 (68% identical), zebrafish calhm2.1 (56% identical), zebrafish calhm2.2 (51% identical), Caenorhabditis elegans clhm-1 (21% identical). Paralogues in human: CALHM3 (28% identical), CALHM4 (28% identical), CALHM1 (26% identical), CALHM5 (26% identical), CALHM6 (26% identical).
Diseases named in the same sentence as CALHM2 in open-access papers:
CALHM2 is named in the same sentence as 8 diseases in open-access papers, as found by Europe PMC text mining. Sharing a sentence is not in itself a finding about the gene and the disease. The quoted sentences say what the papers report.
Cognitive impairment (3 papers, 2022 to 2023). Abnormal cognition is characterized by deficits in thinking, reasoning, or remembering. "In 5×FAD mice harboring five familial AD gene mutations, the conventional knockout (KO) of Calhm2 and the conditional microglial KO of Calhm2 demonstrated a significant decrease in Aβ deposition, neuroinflammation, and cognitive impairments." (PMID 38259497, 2023). "Our previous study found that Calhm2 expression was increased in AD model mice, and that knockout of Calhm2 improved Aβ plaque deposition, reduced neuroinflammation, and improved cognitive impairment in AD model mice." (PMID 37064868, 2023). "In particular, in 5×FAD mice carrying five familial AD gene mutations, both conventional knockout of Calhm2 and conditional microglial knockout of Calhm2 significantly reduce Aβ deposition, neuroinflammation, and cognitive impairments." (PMID 36078138, 2022).
Alzheimer disease (1 paper, 2023). A progressive, neurodegenerative disease characterized by loss of function and death of nerve cells in several areas of the brain leading to loss of cognitive function such as memory and language. "We previously reported that Calhm2 regulated microglial activation-mediated neuroinflammation and played an important role in the pathology of Alzheimer's disease." (PMID 37064868, 2023).
congenital heart disease (1 paper, 2024). A heart disease that is present at birth. "Finally, we originally identified CALHM2 in a patient with congenital heart disease and heterotaxy, suggesting it could have a role in embryonic patterning." (PMID 39315269, 2024).
Parkinson disease (1 paper, 2023). A progressive degenerative disorder of the central nervous system characterized by loss of dopamine producing neurons in the substantia nigra and the presence of Lewy bodies in the substantia nigra and locus coeruleus. "In this study, we used conventional Calhm2, neuronal Calhm2, and microglial Calhm2 knockout mice to explore the role of Calhm2 in Parkinson's disease." (PMID 37064868, 2023).
tumor (3 papers, 2020 to 2024). "We have recently conducted a study in which an in vivo CRISPR screen and orthogonal single-cell profiling of infiltrating NK cells across different tumor models have convergently identified the novel NK suppressor Calcium homeostasis modulator family member 2 (CALHM2)." (PMID 39134804, 2024).
neurological disease (1 paper, 2023). "Our results suggest that targeting Calhm2 could be a possible way to reduce neuroinflammation and thereby improve neurological disease." (PMID 37064868, 2023).
respiratory diseases (1 paper, 2021). "More studies are needed to define the functional role of CALHM1 and CALHM2 in sustained pulmonary vasoconstriction and vascular stiffen in the development of PAH and PH due to respiratory diseases and/or hypoxia." (PMID 34408668, 2021).
CALHM2 also shares sentences with these, for which no sentence is quoted: depression (1 paper).